CASP1 (caspase 1)
Diseases named in the same sentence as CASP1 in open-access papers (continued):
Sharing a sentence is not in itself a finding about the gene and the disease.
cancer (continued). "Pro-IL-18 is also cleaved by caspase-1 into its mature form and has been reported to play both beneficial and detrimental roles in the progression of cancer." (PMID 26378020, 2015). "In order to delineate the function of inflammasomes in other cancer types, we evaluated the expression patterns of AIM2, RIG-I, NLRP3, ASC and caspase-1 in 114 cancer cell lines involving 22 cancer types." (PMID 23065753, 2012). "We transduced cancer cells to overexpress crmA which inhibits initiator caspases including caspase-1 and caspase-8 in the death-receptor pathway, or Bcl-2, a well-known inhibitor of multiple caspases in the mitochondrial pathway." (PMID 19247489, 2009). "CASP1 was not only responsible for release and maturation of pro-inflammatory cytokines, but it also initiated pyroptosis, a type of programmed cell death that further amplifies the inflammatory response and influences cancer progression." (PMID 40535567, 2025). "The stimulation of the TLR4 and RAGE signaling pathways by HMGB1 may promote cancer invasion and metastasis via caspase-1 activation and a cascade of inflammatory responses." (PMID 40331953, 2025). "Notably, CASP1 was consistently elevated in normal tissues across most cancers, whereas FOXP3 and PDIA3 were frequently enriched in tumors." (PMID 41150760, 2025). "Moreover, aurigene 1 or AUPM 170 23 an oxadiazole-containing anti-neoplastic agent is employed in lung carcinoma and prompts pyroptosis in cancer cells through the activation of caspase-1 and GSDMD." (PMID 39316325, 2025). "We found that compared to CTNNB1 WT carcinomas, samples harboring CTNNB1 mutations showed significantly decreased levels of IL1A (p-value = 0.045), IL1B (p-value = 0.12), and caspase 1 (p-value = 0.037), while demonstrating similar IL1R1 and IL1R2 expression levels." (PMID 41227323, 2025). "Whether caspase-1 is also involved in TRAIL-R1 signaling in NSCLC cancer cells is unknown; however, enhanced (pro)caspase-1 might play a role in TRAIL-induced apoptosis in A549BTZR cells." (PMID 38835345, 2024). "Pyroptosis is dependent on caspase-1 activation and gasdermin cleavage to induce cancer cell death." (PMID 36763290, 2023). "Similarly, SCLC cell lines had low expression levels of STING and CASP1 across most cancer cell lines from CCLE dataset." (PMID 35957613, 2023). "Moreover, inhibition of caspase-1 and ROS attenuated the effects of simvastatin on cancer cell viability." (PMID 37974278, 2023). "Inflammasomes regulate the activity of caspase-1 and the maturation of IL1β and IL-18, which act as innate immune system sensors and receptors in various infections, cancer, and other diseases, among which the NLRP3 inflammasome has been well characterized to date." (PMID 35457287, 2022). "Moreover, ATP from dying cancer cells promotes proteolytic maturation of caspase-1 and cleavage and release of interleukin (IL)-1β." (PMID 36212143, 2022). "In summary, our results demonstrated that AIM2 expression was low in BRAF-mutant CRC, and restoration AIM2 expression in BRAF-mutant CRC cells could inhibit cancer cell growth in a caspase-1-dependent manner." (PMID 33842454, 2021). "NLRP3 inflammasome activation, caspase-1 activation, release of IL-1β and IL-18 pro-inflammatory cytokines and gasdermin D-mediated pyroptotic cell death are important mechanisms involved in inflammation-induced cancer." (PMID 34452150, 2021). "In principle, inhibition of MyD88-mediated signaling by caspase-1 cleavage might be able to inhibit cancer growth." (PMID 35069570, 2021). "Furthermore, the key genes correlated with KMO, such as the MYD88, IRF1, IL-18, and CASP1 genes, manipulate the inflammation where many cancers arise." (PMID 34683090, 2021). "The transform value of targeting caspase 1 in cancer treatment still needs further exploration." (PMID 34820372, 2021). "However, in MDA/MB 231 cancer cells, caspase-1 activation was significantly higher in P.CNF.1 and further increased in P.CNF." (PMID 34452150, 2021).
cancer (continued). "Therefore, we performed a detailed analysis of cancer versus normal samples to explore the relationship between CASP1 and AML." (PMID 33999861, 2021). "Therefore, the activation of caspase-1 plays an important role in inhibiting the proliferation of cancer cells, and the compounds with an activating NLRP3 inflammasome effect have the potential to be the treatments for NSCLC." (PMID 31941010, 2020). "Unlike healthy breast cells, low expression of CASP1 in various types of cancer, including BC, is closely associated with decreased apoptosis and cancer cell enhancement." (PMID 33297339, 2020). "Additionally, caspase-1 (CASP1) has been reported as a direct target gene of c-Ets-1 in cancer cells." (PMID 31025089, 2019). "Due to the flagellin-induced IL6, which is known to inhibit apoptosis in many cancer cell types, we measured the effects of flagellin on the caspase-1 activity of the C26 cells together with either TLR5 antagonist or genipin, which inhibits NLRP3-mediated inflammasome activation." (PMID 31731747, 2019). "Our results showed that caspase-1 inhibitor at 100 μM could protect cancer cells from pyroptotic cell death induced by DHA." (PMID 29386662, 2018). "It is well established that, caspase-1 primarily activates IL-1β and IL-18 in cancer." (PMID 28974683, 2017). "These included genes involved in cell death and survival processes (BCLAF1, CFLAR, CASP1, and XIAP), genes associated with proliferation-driving transcription or cancer (KLF4, LEF1, SOX4, ID3), and genes associated with inflammation (CD28, CCR7, CX3CR1 and IFNG)." (PMID 28407008, 2017). "In a word, dominance of the dual effects of caspase-1 may depend on the stage of cancers and specific cellular compartments in which it functions." (PMID 28360909, 2017). "Furthermore, all the caspases except caspase-1 are activated by I-Trp treatment in these cancer cells." (PMID 28906489, 2017). "OV infection of a cancer cell results in cell death by multiple mechanisms, including apoptosis, pyroptosis (caspase-1-dependent cell death), autophagic cell death, and necrosis, which is often dependent on either the virus type, the cancer cell type or a combination of both." (PMID 28536385, 2016). "Additionally, pharmacological modulation of the Arg/N-degron pathway, including that of the yet-unidentified caspase-1 level regulator, may provide an alternative therapeutic avenue of targeting cancer cell death." (PMID 40520087, 2025). "A recent study on the correlation between the occurrence of TAMs pyroptosis and cancer progression utilizing single-cell RNA-sequencing analysis demonstrated that human glioma-infiltrating macrophages, MDMs in particular, had significant co-expression of caspase-1 and GSDMD genes." (PMID 38576612, 2024). "When interacting with danger associated molecules (DAMPs) derived from cancer cells, membrane components of innate immunity, such as pattern recognition receptor (PRR), trigger a response of inflammasomes, resulting in activation of caspase-1, which cleaves pro-IL18 and produces IL-18." (PMID 38298540, 2023). "An interesting question is whether caspase-1 inhibitors promote or suppress cancer cell growth." (PMID 36932407, 2023). "IL-18 is a pro-inflammatory and immunomodulatory cytokine of the IL-1 family that is converted from an inactive precursor protein (pro-IL18) by caspase-1-induced cleavage of an N-terminal fragment and may have anti-cancer and oncogenic effects depending on the tissue and cellular environment." (PMID 36743929, 2022). "Interestingly, CASP5 mutations are associated with cancers, while CASP1 and CASP4 mutations are not, suggesting a caspase‐5‐specific protective role against tumorigenesis that is in keeping with SASP‐driven senescence surveillance." (PMID 30916891, 2019).
cancer (continued). "In turn, caspase-1 enhances the proteolytic cleavage and the secretion of the inflammatory cytokines interleukin (IL)-1β and IL-18, leading to infiltration of more immune cells and resulting in the generation and maintenance of an inflammatory microenvironment surrounding cancer cells." (PMID 30619282, 2018). "And curcumin inhibited inflammation-related cancer cell proliferation by reducing IL1B maturation and release through inhibition of CASP1 activation." (PMID 40535567, 2025). "Although conflicting effects on cancer progression have also been described for IL18 and PPARγ, both can promote M2-like TAM differentiation, reversible by caspase-1 inhibition." (PMID 39353903, 2024). "The NLRP3 inflammasome consists of the adaptor and effector proteins NLRP3, Caspase-1, and ASC, which are abundantly produced by cancer cells." (PMID 38904007, 2024). "Accumulating evidence has indicated that caspase-1 is a major regulator of pyroptosis and caspase-3 is a key protease in apoptosis in photosensitizers-PDT-induced cancer." (PMID 37630186, 2023). "Accumulating evidence has demonstrated that caspase-1 plays a crucial regulatory role in apoptosis and pyroptosis induced by PDT in cancer cells." (PMID 37630186, 2023). "Ophiopogonin B, derived from Dioscorea bulbifera L., can induce caspase-1/GSDMD-dependent pyroptosis in lung cancer cells, especially exhibiting a more significant suppression of growth in DDP-resistant cancer cells." (PMID 38239395, 2023). "The result revealed that the expressions of NOD2, CASP1, IL6, and NLRP6 were negatively correlated with some or most drugs, while IL6 was also positively correlated with WZ3105 and MPS‐1‐IN‐1 in the cancer therapeutics response portal database." (PMID 35574984, 2022). "Cleaved IL-1, caspase 1, and LDH levels increased in HEK293T and H1299 cells when NLRC4 was overexpressed, implying the death of more cancer cells." (PMID 36437954, 2022). "Importantly our data suggest that inhibiting Caspase-1 with VX765 has the most potent anti-cancer effects, inhibiting bone metastasis whilst having the least detrimental effect on systemic immunity, suggesting that this drug may be the best option for future development." (PMID 36230739, 2022). "The pyroptosis regulators with CNV amplification were significantly more highly expressed in cancer cells (e.g., GSDMD), whereas the regulators with CNV deletion were significantly less expressed (e.g., CASP1, CASP3, and CASP4)." (PMID 35620284, 2022). "A majorly pan-cancer positive correlation between promotor methylation and gene expression of GSDMA, CASP1, NLRP9, GZMB, DHX9, DDX3X, SFRS2IP (CASP11) and GPX4 was observed." (PMID 36605187, 2022). "Many of the deregulated genes seem to be directly connected to GWAS or cancer driver genes such as TLR8, CASP1, and TNFRSF10B." (PMID 33717131, 2021). "Treating human-derived macrophages with the supernatants from co-cultured CD19-CAR-T cell and cancer cells (NALM-6, Raji, or primary B leukemic cells) prompted macrophage activation of caspase-1, cleavage of GSDMD, and release of IL-6 and IL-1β." (PMID 34429144, 2021). "When cancer cells were co-cultured with TAM, we found that the expression of NLRP3, AIM2, cleaved-caspase 1, and IL-1β was significantly upregulated." (PMID 34815793, 2021). "ZR 75-1 cancer cells released lower levels of caspase-1, compared with MDA/MB 231 cancer cell, suggesting the aggressiveness of triple negative BC." (PMID 34452150, 2021). "Here, we performed data mining on the expression and prognosis of CASP1 in AML patients from the Cancer Genome Atlas (TCGA) and multiple cancer databases." (PMID 33999861, 2021). "Further, western blot assays showed that caspase-1 and IL-1β expression levels were downregulated in RCC cancer tissues, indicating the same trend." (PMID 32303673, 2020).
cancer (continued). "Cancer cells were treated with Ivermectin and analyzed for 1) PARP cleavage; 2) activation of caspase-1-a characteristic feature of the pyroptotic cell death pathway; and 3) caspase-3 activity typically observed in classical apoptosis." (PMID 26552848, 2015). "First, we interrogated the expression of NLRP3, CASP1, and IL‐1β in 90 pediatric ALL PDX samples (Pediatric Preclinical Testing Consortium [PPTC] data set) that served as a platform for choosing the most suitable PDX model to study MCC950 effects on cancer." (PMID 40104043, 2025). "A critical remaining question is the identification of an Nt-arginylation-permissive substrate that regulates caspase-1 protein levels via either transcription or degradation, thereby affecting RILP cleavage and its downstream exosome formation in cancer cells." (PMID 40520087, 2025). "Recently, pyroptosis, a type of nonapoptotic cell death mediated by caspase-1, has garnered attention in cancer research." (PMID 38562170, 2024). "NLRP3 inflammasome is composed of NLRP3, apoptosis-associated speck-like protein containing CARD (ASC) and effector pro-caspase-1, and can affect the occurrence and development of IBD and even cancer via regulating the maturation, secretion, and pyroptosis of IL-1β and IL-18." (PMID 38650627, 2024). "Nowadays, the caspase-1/GSDMD and caspase-3/GSDME pathways have attracted significant attention in pyroptosis induction, and many natural compounds have been found to activate these pathways in cancers." (PMID 38239395, 2023). "From the lncRNA-mRNA pathway network, PYCARD, RIPK2, and CASP1 were found to be significantly enriched in the NOD-like receptor signaling pathway, whereas MAP2K2, LUM, RPS6, PDCD4, TWIST1, and HIF1A were significantly enriched in proteoglycans in cancers." (PMID 36619896, 2022). "Other caspase-1 inhibitors used in inflammatory diseases, such as Pralnacasan or VX-765 (Belnacasan) are not yet in use in cancer clinical trials." (PMID 35517498, 2022). "A third group of cancers comprised of BLCA, BRCA, UCEC, LIHC, STAD, PRAD and THCA showed a similar expression pattern with first group of cancers except for the contrast behavior of NLRP3, NLRC4, PRF1, CASP1, CASP4, and GZMA (downregulated in this group)." (PMID 36605187, 2022). "The pyroptotic effects in cancer cells are mediated by the activation of caspase-1, whereas the release of IL-1β in normal cells appears to be both dependent and independent of caspase-1." (PMID 35082671, 2021). "BCL2L1 inhibits caspase-1 activation by interfering with NLRP1 oligomerization, a key component of the inflammasome immune response, and ITP3 has an anti-apoptotic effect in mammalians cancer cells." (PMID 33676414, 2021). "Collectively, the expression of NLRP3, caspase-1, GSDMD, and IL-1β protein was higher in cancer and atypical hyperplasia tissues than in benign endometrial tissues, significantly difference were observed in key pyroptotic protein caspase-1 and GSDMD (P < 0.05)." (PMID 31924176, 2020). "LINC00261, TNFRSF11A, CASP1, ST6GALNAC1, and PIGR also play prognostic roles in cancer." (PMID 31689990, 2019). "Moreover, NLRP3 inflammasome components ASC and Caspase-1 were also highly expressed in SCCHN tissues and cancer cell lines." (PMID 28865486, 2017). "The five EV-dependent regulated genes whose expression changes were prevented by importazole (i.e. ghrelin, IL-26, IL-17B, Casp1 and CCL5) may be relevant for the pro-tumorigenic activity of cancer EVs." (PMID 28129640, 2017). "Similarly, inhibition of Casp1 and Casp6 by methylene blue could have beneficial effects by reducing inflammatory processes and axonal degeneration, but inhibition of Casp3 could alter neuronal function or promote cancer cell survival and be detrimental to tissue homeostasis." (PMID 26400108, 2015).
cancer (continued). "Therapeutically, strategies aiming to restore CASP1 activity, deplete or inhibit FOXP3+ Tregs, or target PDIA3-related antigen presentation defects could enhance immune surveillance and improve responsiveness to immunotherapy in multiple cancer types." (PMID 41150760, 2025). "Additionally, UBASH3B, CASP1, CARM1, CHAF1B and PCNT have been studied in other cancers." (PMID 37894336, 2023). "Triggered by a hypoxic microenvironment, highly expressed ERRα could bind to the promoter of NLRP3 and inhibit caspase-1/GSDMD signaling, which reduced inflammasome activation and increased pyroptosis resistance, thereby resulting in the resistance of cancer cells to cisplatin." (PMID 37864196, 2023). "In our proposed DMD-related lncRNA-mRNA pathway networks, PYCARD, RIPK2, and CASP1 were significantly enriched in the NOD-like receptor signaling pathway, whereas MAP2K2, LUM, RPS6, PDCD4, TWIST1, and HIF1A were significantly enriched in proteoglycans in cancers." (PMID 36619896, 2022). "And, strictly speaking, as knockdown of MEG3 only partly abolished the activation of DDP-induced NLRP3/caspase-1/GSDMD pathway and anti-cancer functions in MDA-MB-231 cells, MEG3 may partially mediated the pyroptotic signaling upon DDP treatment in this type of TNBC cell line." (PMID 34326697, 2021). "All together, these results indicate that MILH and doxorubicin separately induce the death of cancer cells by two different mechanisms, corresponding to the activation of a non-apoptotic and an apoptotic pathways depending on Caspase-1 and Caspase-3 activation, respectively." (PMID 29954075, 2018). "In fact, neither neutralization of the low amounts of IL-1β produced after PolyIC-treatment of the cancer cells nor caspase-1 or pan-caspase inhibitors, both of which have the potential to interfere with IL-1β processing and activation, significantly inhibited DC activation." (PMID 25888634, 2015). "Therefore, we wondered whether caspase-1 plays a role on the absence of deamidated HsTIM in normal cells in contrast with its accumulation in cancer cells." (PMID 35256749, 2022). "Another study indicated that lactoferrin could up-regulate the components of non-specific immunity against cancer, including interferon-γ (IFN-γ), caspase-1 and interleukin-18 (IL-18)." (PMID 38298540, 2023). "To determine whether NLRP3 inflamasome was associated with human HNSCC, we examined their expression by immunohistochemistry and found that NLRP3, Caspase-1, ASC, IL-18 were highly expressed in the cytoplasm of cancer cells, and the expression of them was negative or low in the normal mucosa." (PMID 28865486, 2017).